ASCL2 (achaete-scute family bHLH transcription factor 2)
Diseases named in the same sentence as ASCL2 in open-access papers (continued):
Sharing a sentence is not in itself a finding about the gene and the disease.
prostate carcinoma (3 papers, 2014 to 2024). A carcinoma that arises from epithelial cells of the prostate gland. "Knockout of TFAP4 was found to decrease ASCL1/2 expression, inhibiting cell growth in ASCL1+ prostate cancer cells but causing a drastic increase in ASCL2+ cells." (PMID 39372390, 2024). "In NE prostate cancer, a novel molecular subtype of prostate cancer has been identified, consisting of class I (ASCL2+) and class II (ASCL1+) types." (PMID 39372390, 2024). "ASCL1 and ASCL2 are mutually exclusive during NEtD in prostate cancer, similar with the relationship between MYCL and MYC in SCLC and FOXA2 and FOXA1 in NEPC." (PMID 39372390, 2024). "By inspection, we also identified at least 10 additional transcription factors within 500 kb of 9 other GWAS loci, that are also reasonable candidates for contributing to prostate cancer risk: SOX13, ZFP36L2, ATOH8, DLX1 & DLX2 (same locus), GATA2, SKIL, SP8, ASCL2, and DPF1." (PMID 24497837, 2014).
virus infection (3 papers, 2017 to 2025). "Furthermore, we develop an original strain of mice with conditional deletion of Ascl2 in NK cells and employ this new transfer model to demonstrate a role for ASCL2 in enrichment of NK cells in the spleen and white pulp after virus infection." (PMID 40694683, 2025). "It is possible that cellular stressors, such as inflammation and virus infection, might lead to up-regulation of acute responders like Ascl2, and trigger an attempt for NSCs to deal with the exogenous changes/challenges." (PMID 31788333, 2019).
Barrett esophagus (2 papers, 2022 to 2024). Esophageal lesion lined with columnar metaplastic epithelium which is flat or villiform. "More recently, high expression of ASCL2 in esophageal adenocarcinoma was proposed as a poor prognosis of survival." (PMID 38252116, 2024). "Multivariate Cox regression analysis revealed that ASCL2 expression is an independent prognostic factor for esophageal adenocarcinoma (OS; WS p=0.25, TMA p=0.011." (PMID 35154991, 2022). "High expression of the intestinal stem cell marker ASCL2 may predict unfavorable outcomes in surgically resected esophageal adenocarcinoma." (PMID 35154991, 2022). "Furthermore, our studies suggest that ASCL2 is implicated in the early stage of EAC carcinogenesis, which may provide additional evidence to the role of intestinal stem cells in Barrett's esophagus formation." (PMID 35154991, 2022).
colon adenoma (2 papers, 2019 to 2021). An adenoma that arises from the colon. "The goal of the present study was to determine the efficacy of a novel Ascl2 targeted KISIMA vaccine in stimulating an immune response and inhibiting the formation of colon adenomas in Apc+/Min-FCCC mice." (PMID 33671373, 2021).
colorectal adenoma (2 papers, 2019 to 2021). An adenoma that arises from the colon or rectum. "As in humans, colorectal adenomas in the Apc+/Min-FCCC model overexpress the murine form of Ascl2, murine achaete scute homolog 2 (Mash2)." (PMID 33671373, 2021).
esophageal cancer (2 papers, 2021 to 2025). A primary or metastatic malignant neoplasm involving the esophagus. "ASCL2 functions as a master regulator of stemness in small intestinal epithelium where it activates its own expression and that of downstream Wnt effector and receptor genes, and in esophageal cancer, although its role in colon epithelium had not been studied in detail." (PMID 39895630, 2025).
gastric tumor (2 papers, 2022 to 2023). "It was able to downregulate the expression level of miR223, contribute to EMT (the epithelial-mesenchymal transition), and promote gastric tumor metastasis, which indicated that ASCL2 might serve as a therapeutic target in the treatment of GC." (PMID 36936373, 2023). "In this study, we indicate that the ASCL2 inhibition could significantly activate inflammation, weakening the development of tumor cells, and decreasing the level of biomarkers of gastric tumor through TLR4 activation." (PMID 36008864, 2022).
lung squamous cell carcinoma (2 papers, 2017 to 2018). "In addition, elevated ASCL2 expression is associated with the metastasis of osteosarcoma and lung squamous cell carcinoma and predicts poor prognosis in these patients." (PMID 29805736, 2018). "In addition, elevated ASCL2 expression is associated with the metastasis of osteosarcoma and lung squamous cell carcinoma and predicts poor prognosis of these patients." (PMID 29805736, 2018).
osteosarcoma (2 papers, 2017 to 2018). A usually aggressive malignant bone-forming mesenchymal neoplasm, predominantly affecting adolescents and young adults. "Elevated ASCL2 expression in patients with osteosarcoma is also associated with osteosarcoma metastasis and poor prognosis." (PMID 28757546, 2017).
autoimmune disease (1 paper, 2025). A disorder resulting from loss of function or tissue destruction of an organ or multiple organs, arising from humoral or cellular immune responses of the individual to their own tissue constituents. "This and future studies are likely to reveal ASCL2-regulated pathways vital for immunoregulatory functions of NK cells that can be targeted to circumvent NK cell suppression of vaccine response or to bolster NK-cell based therapies targeting pathogenic T and B cells in autoimmune disease." (PMID 40694683, 2025).
Beckwith-Wiedemann syndrome (1 paper, 2019). Beckwith-Wiedemann syndrome (BWS) is a genetic disorder characterized by overgrowth, tumor predisposition and congenital malformations. "Highly expressed in the skin, ASCL2 is associated with Beckwith-Wiedemann syndrome, which is the most common pediatric overgrowth syndrome." (PMID 31639064, 2019).
brain tumor (1 paper, 2009). "Among those genes are ASCL2 and ASCL3, mammalian homologues of Drosophila achaete-scute complex, as well as TRIM3, a homologue of Drosophila brain tumor involved in progenitor cell proliferation control and cancer stem cell suppression, and a cluster of more distantly related TRIM genes." (PMID 19250537, 2009).
colorectal adenocarcinoma (1 paper, 2012). The most common type of colorectal carcinoma. "Immunohistochemistry demonstrated that Ascl2 was significantly increased in colorectal adenocarcinomas." (PMID 22384170, 2012).
colorectal tumors (1 paper, 2021). "Second, Ascl2 is induced during the formation and progression of colorectal tumors, with minimal expression observed in non-neoplastic tissue." (PMID 33671373, 2021).
cyst (1 paper, 2017). A sac-like closed membranous structure that may be empty or contain fluid or amorphous material. "Interestingly, the Hmga1 organoids generated from purified Lgr5+ ISCs adopt a cyst-like, spherical structure similar to the morphology observed in organoids treated with Wnt or engineered to overexpress Ascl2, a transcription factor important in maintaining stem cell identity in ISCs7." (PMID 28452345, 2017).
diabetes (1 paper, 2012). "However, Ascl2 is only regulated by diabetes, not by diet (unpublished observations), and thus cannot account for the greater extent of growth reduction of diabetic placentas in breeder diet-fed dams." (PMID 22701643, 2012).
dysplasia (1 paper, 2022). A usually neoplastic transformation of the cell, associated with altered architectural tissue patterns. "EAC showed significantly increased ASCL2 expression compared to the normal (p<0.001) and Barrett (p<0.001) and a trend towards higher expression compared to dysplasia (p=0.0686)." (PMID 35154991, 2022).
intestinal tumors (1 paper, 2023). "Quantitative RT-PCR analysis of the isolated tumors showed that expression of the WNT target genes and stem cell markers Lgr5, Ascl2, and Axin2 were suppressed in the Usp7 cKO tumors, suggesting that Usp7 depletion inhibits WNT signaling in the Apc-deficient intestinal tumors." (PMID 36669491, 2023).
Lynch syndrome (1 paper, 2021). An autosomal dominant hereditary neoplastic syndrome characterized by the development of colorectal carcinoma and a high risk of developing endometrial carcinoma, gastric carcinoma, ovarian carcinoma, renal pelvis carcinoma, and small intestinal carcinoma.
melanoma (1 paper, 2024). A malignant, usually aggressive tumor composed of atypical, neoplastic melanocytes. "ASCL2 was highly expressed in breast, colon, gastric, lung, head and neck, ovarian, and testicular cancers, while is less expressed in sarcoma, melanoma, brain, and prostate cancers." (PMID 38951569, 2024).
pulmonary fibrosis (1 paper, 2020). Chronic progressive interstitial lung disorder characterized by the replacement of the lung tissue by connective tissue, leading to progressive dyspnea, respiratory failure, or right heart failure. "In a similar way to ASCL2, the original SCX function was described as relevant in embryonic development; however, its high abnormal expression in tissue characterizes pulmonary fibrosis." (PMID 32708589, 2020).
type 2 diabetes (1 paper, 2018). "Nine genes not previously reported to be associated with type 2 diabetes were significantly dysregulated in our organ donor and PPP cohorts (ANKRD23/39, ASCL2, HHATL, NSG1, PCDH20, SCTR, CD44, FAM102B and FBXO32)." (PMID 29185012, 2018).
tumor (44 papers, 2009 to 2026). "In despite of which the literature indicates that ASCL2 is silenced by CpG island methylation during the progression of tumorigenesis, its re-expression is associated with reduced tumor growth." (PMID 37591954, 2023). "The results indicate that miR-302b is an important miRNA related to the inhibition of cancer progenitor cells caused by Ascl2 selective blockade in HT-29 cells, which led to tumor growth arrest in vivo and in vitro." (PMID 22384170, 2012). "RT-qPCR and Western blot analyses confirmed that CTHRC1, APOD, and S100A12 expression was significantly upregulated in the tumor group, while ASCL2 expression was significantly downregulated." (PMID 40898459, 2025). "Reverse transcription quantitative polymerase chain reaction and Western blot analyses confirmed that CTHRC1, APOD, and S100A12 were significantly upregulated in the tumor group, whereas ASCL2 expression was significantly downregulated." (PMID 40898459, 2025). "The results showed that the expression levels of CTHRC1, APOD, and S100A12 in the tumor group were significantly upregulated, whereas the expression levels of ASCL2 in the tumor group were significantly downregulated." (PMID 40898459, 2025). "In this study, it is demonstrated that knockout of mutant FAT1 in HNSCC cells attenuates CPT1A‐driven fatty acid oxidation (FAO) through downregulation of the transcription factor ASCL2, leading to marked suppression of tumor growth." (PMID 40407216, 2025). "ASCL2 is a member of a family of transcription factors that play a role in several aspects of tumours." (PMID 38613794, 2024). "The scatter plot unveiled a notably stronger correlation between CDC25A and the tumor stemness index compared to ASCL2." (PMID 38613794, 2024). "This PARCB model generates two distinct tumor lineages characterized by either stem-like (POU2F3/ASCL2 subtype) or neuroendocrine features (ASCL1 subtype) that closely resemble the POU2F3 and ASCL1 subtypes seen in clinical SCNCs." (PMID 39589879, 2024). "Immunotyping of single cells isolated from tumor tissues and immunohistochemistry (IHC) analysis revealed that Ascl2 markedly decreased the number of tumor-infiltrating CD8+ T cells, CD4+ T cells, and CD11C+ CD11B- DCs, suggesting immune activation in the TME." (PMID 37591954, 2023). "Consistent with the subcutaneous tumorigenesis assay in C57BL/6 mice, downregulation of Ascl2 observably increased the number of tumor-infiltrating CD8+ T cells in primary CRC tumors." (PMID 37591954, 2023). "In this way, DPEP1 and ASCL2 formed a positive feedback loop regulation mode, which increased the tolerance of tumor cells to chemotherapeutic drugs." (PMID 35670012, 2023). "Activated CD8+ T cells migrated from the upper compartment when they were co-cultured with 3D tumor spheres, while the CD8+ T cells cocultured with ASCL2-downregulated 3D tumor spheroid had a stronger migration." (PMID 37591954, 2023). "Our findings reveal that the DPEP1 enhances the stemness of tumor cells by forming a positive feedback loop with ASCL2 to improve resistance to chemotherapy drugs." (PMID 35670012, 2023). "DPEP1 and ASCL2 formed a positive feedback loop regulation mode, which increased the tolerance of tumor cells to chemotherapeutic drugs." (PMID 35670012, 2023). "The ASCL2 level in STAD tumor tissues is increased, compared to normal tissues, and brings a worse prognosis." (PMID 36008864, 2022). "Next, we use sparstolonin B to activate the TLR4 signal for confirming the tumor-regulated effect of the ASCL2, following which we observe the changes." (PMID 36008864, 2022). "This implies that ASCL2 can indirectly affect the tumor immune microenvironment by regulating the expression of downstream target gene DUSP4." (PMID 35774798, 2022). "The study aims to investigate the potential role and function of ASCL2 in STAD, then apply ASCL2 knockdown lentivirus (sh-ASCL2) to enhance apoptosis, inflammatory progress, and tumor development in vivo and in vitro." (PMID 36008864, 2022).
tumor (continued). "Further, ASCL2 was shown to indirectly affect tumor immune cell infiltration by negatively regulating the expression of DUSP4." (PMID 35774798, 2022). "In conclusion, this study revealed that ASCL2 was positively correlated to CSCs and tumor immune infiltration in COAD." (PMID 35774798, 2022). "The ASCL2 expression is induced in tumor tissues or cells, which is coincident with the previous analysis." (PMID 36008864, 2022). "In brief, our findings elucidated that ASCL2 correlated with CSCs and tumor immune infiltration in COAD." (PMID 35774798, 2022). "To analyze if DNA hypomethylation suppresses intestinal tumorigenesis in Uhrf1ki/ki/ApcMin/+ mice by affecting tumor stem cells, we examined the levels of intestinal stem-cell marker genes Lgr5, Ascl2, and Sox9 by qRT-PCR." (PMID 33947834, 2021). "This shift is consistent with the observation that chemo- and immunoprevention strategies that target the stem cell compartment, including atorvastatin and a vaccine against Ascl2, are most effective when administered prior to tumor formation." (PMID 34513688, 2021). "Validating these findings, we found expression of canonical WNT target genes AXIN2, LGR5, TCF7 and ASCL2 were elevated in tumours expressing high levels of RAC1B." (PMID 33879799, 2021). "The analysis confirmed a (moderate) increase in the expression of Ascl2 and other Wnt target genes Axin2, Lgr5, and SP5 in Apc/Msx−double-deficient tumor cells when compared to the cells with intact Msx1 gene." (PMID 30733598, 2019). "In one case of LGD, Smoc2 appeared to be limited to tumor bases, but Lgr5 and Ascl2 showed diffuse and patchy distribution." (PMID 28747693, 2017). "Entero/Goblets were mainly early stage tumours whereas ASCL2/MYC and ECM/EMT were rather late stages." (PMID 28186126, 2017). "In mouse, Snail family members Snai 1 and Snai 2 can compete with HLH family member Ascl2 to bind to E2 box, regulating expression of tumor repressor Epbh3 to control tumor metastasis." (PMID 28428611, 2017). "The expression of OLFM4, EPHB2, and ASCL2 was relatively restricted to the basal region of tumor glands in the GA with basal LGR5 expression, but the expression of these markers was diffuse in the GA with a diffuse LGR5 expression pattern." (PMID 24340024, 2013). "Ascl2 expression in tumor tissue from shRNA-Ascl2/HT-29 or shRNA-Ascl2/LS174T cells was significantly lower than that from shRNA-Ctr/HT-29 or shRNA-Ctr/LS174T cells, as shown by immunohistochemical staining." (PMID 22384170, 2012). "Differential expression analysis of these 27 intersecting genes in the GSE87211 dataset from GEO revealed significant expression differences between tumor and normal groups for 26 genes, with ASCL2, IFITM3, IFITM1, SMPDL3A, and SUCLG2 being the five most significantly differentially expressed." (PMID 41595533, 2026). "Indeed, ASCL1 overexpression in two PARCB POU2F3/ASCL2 tumor-derived cell lines led to increased PGC-1α expression in both cell lines." (PMID 39589879, 2024). "Furthermore, we found that Ascl2 contributed to excluding CD8+ T cells from tumor parenchyma through activated CAFs." (PMID 37591954, 2023). "Similarly, RT-PCR was used to examine ASCL2 expression in 14 paired primary tumors and adjacent normal intestinal mucosa, and the results showed significantly higher level of ASCL2 mRNA in the tumor tissues than in the normal tissues." (PMID 37591954, 2023). "Moreover, limiting dilution xenotransplantation assays demonstrated that knockdown of ASCL2 resulted in a lower tumor-initiating frequency and self-renewing capacity, suggesting that ASCL2 is required for self-renewal." (PMID 37591954, 2023). "Furthermore, overexpression of ASCL2 in xenografts accelerated tumor growth, and mice inoculated with ASCL2 enforced‐expression cells survived shorter than those inoculated with control cells." (PMID 35882624, 2022). "The expression of ASCL2 in STAD tumor tissues is increased, which indicates ASCL2 could possibly be an oncogene in STAD." (PMID 36008864, 2022).